TLR4 (toll like receptor 4)
Diseases named in the same sentence as TLR4 in open-access papers (continued):
Sharing a sentence is not in itself a finding about the gene and the disease.
meningitis (16 papers, 2011 to 2025). A disorder characterized by acute inflammation of the meninges of the brain and/or spinal cord. "In conclusion, our study reveals TLR4 as a critical regulator of host responses during ExPEC meningitis, with its deficiency triggering complex adaptations that enhance survival through improved tissue tolerance rather than pathogen clearance." (PMID 40821830, 2025). "At the CNS level, TLR4 participates in the detection of pathogens that cause meningitis, such as Neisseria meningitidis, where some DAMPs linked to brain damage mediate TLR4 signaling." (PMID 34819919, 2021). "Meningococcal strains with such lipid A endotoxin variants have been found previously in adult meningitis patients, where they caused less blood coagulopathy because of decreased TLR4 activation." (PMID 23209568, 2012). "After correction for multiple testing, TLR4+896 mutant alleles were highly associated with post-meningitis hearing loss, especially MM (p = 0.001, OR 4.0 for BM, p = 0.0004, OR 6.2 for MM)." (PMID 22662111, 2012). "This fundamental difference in TLR2 and TLR4 functions during E. coli meningitis provides new insights into how pathogens can differentially engage host receptors, with TLR2 being co-opted for invasion while TLR4 primarily mediates inflammatory damage." (PMID 40821830, 2025). "In this study, we established an ExPEC-induced meningitis model using human brain microvascular endothelial cells (hCMEC/D3) and TLR4 knockout (TLR4-/-) mice to explore the role of TLR4 in endothelial barrier disruption during bacterial meningitis." (PMID 40821830, 2025). "Strikingly, the meningitis phenotype of Tlr2–/– Tlr4–/– (Tlr2/4–/–) double-knockout (double-KO) mice was stronger than that of Tlr2–/– mice, yet significantly milder than that of Myd88–/– mice." (PMID 38358825, 2024). "Subsequent comparative analyses in an experimental meningitis model, however, implicated the concerted action of TLR2 and TLR4, while negating a role for TLR9 in the innate immunological perception of pneumococcal CNS infection." (PMID 38358825, 2024). "Combined carriership of TLR2+2477 GG (WT) and TLR4+896AG (mutants) increased the risk to develop post-meningitis hearing loss, indicating that TLR2 SNPs compensate for TLR4 mutant hyporesponsiveness." (PMID 22662111, 2012). "Here TLR4 WT (C3H/FeJ) and TLR4 mutant (C3H/HeJ) mice as well as MyD88 KO animals were infected intracerebrally with live C. koseri, resulting in meningitis and ventriculitis with accompanying brain abscess formation." (PMID 21496301, 2011). "Although capable of modulating lung inflammation, singular TLR4 deficiency did not affect meningitis pathology." (PMID 38358825, 2024). "However, a previous study on mouse meningitis induced by E. coli showed that TLRs were activated in brain tissues, with elevated Tlr2, Tlr4 and Tlr7 expression." (PMID 32509459, 2020). "TLR4+896 mutants are highly associated with post-meningitis hearing loss and combined carriership of the TLR2+2477 WT with TLR4+896 mutant alleles as well as the combination of TLR4+896 mutant alleles with TLR9 -1237 mutant alleles significantly increases this risk." (PMID 22662111, 2012). "In addition, patients with meningitis caused by Gram-negative bacteria who were carriers of a variant TLR4 genotype had an increased risk of ataxia and other neurological sequelae than those with a wild-type TLR4 genotype." (PMID 32967147, 2020). "However, previous studies have also shown that the TLR4 polymorphism does not increase the risk of meningococcal or pneumococcal diseases such meningitis or sepsis." (PMID 32967147, 2020). "In this study, patients who had meningitis caused by Gram-negative bacteria and who were carriers of the variant TLR4 genotypes had higher risk of ataxia and other neurological sequelae than those with the wild-type TLR4 genotype." (PMID 32967147, 2020).
meningitis (continued). "Three types of Toll-like receptors (TLR2, TLR4, TLR9) have been identified as the ones that are involved in S. pneumoniae meningitis." (PMID 39121090, 2024).
osteosarcoma (16 papers, 2019 to 2025). A usually aggressive malignant bone-forming mesenchymal neoplasm, predominantly affecting adolescents and young adults. "The result indicated that CCL28, KLF2 and TNFSF18 did not significantly affect cell apoptosis, while the knockdown of HMGB1 and TLR4 significantly increased the proportion of apoptotic of osteosarcoma cells." (PMID 36204682, 2022). "Activation of TLR4 signaling inhibits the progression of osteosarcoma by stimulating CD8+ cytotoxic lymphocytes." (PMID 34660305, 2021). "Our findings indicate that COLEC12 is possibly able to regulate inflammation in osteosarcoma when mediated through TLR4." (PMID 32822099, 2020). "Our findings indicate that COLEC12 knockdown significantly activates inflammation function and inhibits the development of osteosarcoma modulating through TLR4, and then improve the level of osteosarcoma apoptosis, prolonging the lives of mice." (PMID 32822099, 2020). "Clinical observation is in favour of TLR4-based therapeutic option in osteosarcoma." (PMID 35990515, 2022). "The prognostic role of TLR4 in Osteosarcoma remain controversial." (PMID 36204682, 2022). "It has been reported that the activation of TLR4 prevents progression of osteosarcoma, while some other evidence demonstrated the TLR4 related pathway could promote the invasion and migration of Osteosarcoma." (PMID 36204682, 2022). "To eliminate whether TLR4 is involved in the COLEC12 inflammatory function of osteosarcoma, we used TLR4 knockdown lentivirus to block TLR4 expression, which was the preliminary component of inflammation." (PMID 32822099, 2020). "The potential mechanisms of inflammation by COLEC12 mediated through TLR4 in osteosarcoma." (PMID 32822099, 2020). "COLEC12 may be able to regulate apoptosis and inflammation of osteosarcoma, and TLR4 may be the downstream target factor of COLEC12 in inflammation." (PMID 32822099, 2020). "Thus, the role of TLR4 in Osteosarcoma need further more investigations." (PMID 36204682, 2022). "However, it has not yet been reported whether the role of COLEC12 for inflammation in osteosarcoma is regulated by TLR4." (PMID 32822099, 2020). "TLR4 was pivotal promoter of inflammation which related NF‐kB and C3 signaling, and then released TNF‐α and ILs, which can induce apoptosis of osteosarcoma cells." (PMID 32822099, 2020). "While response of osteosarcoma to immunotherapies has not been as good as expected, here we report the dramatic antitumor effect of an IV-administered TLR4 agonist to inhibit OsA’s progression." (PMID 37760603, 2023). "HOTAIR expression markedly increases in LPS-induced EMT in osteosarcoma cells, such as TLR4 (Toll Like Receptor 4), which is the LPS receptor, suggesting that the effects of LPS on EMT in osteosarcoma cells is mediated via the TLR4/HOTAIR pathway." (PMID 34576322, 2021). "Furthermore, COLEC12 knockdown could increase inflammation of osteosarcoma, in vivo and in vitro, through inducing myeloperoxidase (MPO), TLR4, NF‐κB, and C3, and expression of related inflammatory factors." (PMID 32822099, 2020). "However, whether the role of COLEC12 for inflammation in osteosarcoma is regulated by TLR4 has not been reported." (PMID 32822099, 2020).
systemic sclerosis (16 papers, 2010 to 2025). A chronic disorder, possibly autoimmune, marked by excessive production of collagen which results in hardening and thickening of body tissues. "TNC activation of TLR4 also promotes collagen synthesis and fibroblast activation and is strongly associated with the pathogenesis of systemic sclerosis in mice." (PMID 34772945, 2021). "Consistently with a role in fibroblast activation, an amelioration of tissue fibrosis was observed in TLR4 knockout in murine models of systemic sclerosis." (PMID 34487318, 2023). "Activation of TLR4 by its cognate damage-associated molecular patterns (DAMPs) elicits potent profibrotic effects and myofibroblast activation in systemic sclerosis (SSc), while genetic targeting of TLR4 or its DAMPs in mice accelerates fibrosis resolution." (PMID 36136452, 2022). "Another study has reported circulatory macrophage (CD204+CD163+CD206+TLR4+CD80+CD86+) and monocyte (CD14+CD206+CD163+CD204+TLR4+CD80+CD86+) populations that expressed both M1/M2 markers in systemic sclerosis patients and in interstitial lung disease (ILD)." (PMID 35603185, 2022). "In addition, in systemic sclerosis activation of TLR4 on the surface of fibroblasts contributes to the upregulation of profibrotic chemokines." (PMID 29850627, 2018). "TLR2- or TLR4-mediated stimulation was also reported to promote DCs to produce IL-10, induce an augmented Th2 immune response, and aggravate systemic sclerosis (SSc)." (PMID 35619184, 2022). "Fibronectin-EDA and tenascin-C may activate Toll receptor 4 (TLR4) and lead to uncontrolled extracellular matrix (ECM) deposition in systemic sclerosis (SSc), which subsequently enhances transforming growth factor beta (TGF-β) signaling, thus promoting fibrotic responses." (PMID 40843700, 2025). "Thus, TLR4-mediated activation of innate immunity plays a key role not only in host defense against pathogens but also in numerous autoimmune diseases, including systemic sclerosis (SSc)." (PMID 30804934, 2019). "However, excessive activation of TLR2 or TLR4 in dFBs by endogenous DAMPs such as TLR4 ligands hyaluronan, fibrinogen, and other ECM proteins or TLR2 ligand serum amyloid A (SAA) may lead to the pathogenesis of fibrotic skin disorders, such as hypertrophic scarring and systemic sclerosis (SSc)." (PMID 31815151, 2019).
atopic dermatitis (15 papers, 2012 to 2025). "The purpose of the study is to determine the relationship of polymorphisms of genes of Toll-like receptors TLR2 and TLR4 with clinical and immunological parameters in atopic dermatitis patients in a “case-control” study." (PMID 28593178, 2017). "Mast cells directly induce IL-10 expression following Toll-like receptor 4 (TLR4) activation by lipopolysaccharide (LPS) or during allergic dermatitis or skin damage." (PMID 37359549, 2023). "In this study, we evaluated the protective effects of SIG-1451, a non-steroidal anti-inflammatory compound developed for treating atopic dermatitis and known to inhibit Toll-like receptor 4, in light-induced photoreceptor degeneration." (PMID 35955937, 2022). "In the group of patients with atopic dermatitis, the TLR4 A/A genotype frequency was equal to 87,0% (43 persons), while in the control group it was 91,0% (91 persons)." (PMID 28593178, 2017). "This benefit occurs both within and outside the context of pathogen infection, as even without infection, TLR4-deficient mice displayed more severe atopic dermatitis with a stronger T helper 2-driven immune response compared with wild-type mice." (PMID 38067173, 2023). "Interestingly, a decreased TLR4 expression is detrimental to patients with atopic dermatitis, as a decreased expression disrupts the water barrier and increases skin thickness." (PMID 38067173, 2023). "The goal of the present research (actually, a random case-control study) was to elucidate how the polymorphisms of genes TLR2 and TLR4, which encode the TLR2 and TLR4 receptors of the immune response system, are associated with clinical and immunological indicators of atopic dermatitis." (PMID 28593178, 2017). "Genetic variation in TLR2, TLR4, TLR10 and TLR1TLR6 and TLR10 have been associated with the development of asthma, and in TLR9 a promoter polymorphism has been associated with atopic eczema." (PMID 22857391, 2012). "Flow cytometric analysis revealed that the ratios of basophils activated by TLR4 stimulation in type 1 AIP (9.875 ± 1.148%) and atopic dermatitis (11.768 ± 1.899%) were significantly higher than those in healthy subjects (5.051 ± 0.730%; P < 0.05)." (PMID 28921377, 2018). "However, the ratios of basophils activated by TLR4 stimulation in the blood of patients with type 1 AIP (9.875 ± 1.148%) and atopic dermatitis (11.768 ± 1.899%) were significantly higher than that in healthy subjects (5.051 ± 0.730%; P < 0.05)." (PMID 28921377, 2018).
atrial fibrillation (15 papers, 2019 to 2025). A disorder characterized by an electrocardiographic finding of a supraventricular arrhythmia characterized by the replacement of consistent P waves by rapid oscillations or fibrillatory waves that vary in size, shape and timing and are accompanied by an irregular ventricular response. "TLR4, in association with MD-2, detects lipopolysaccharides (LPSs) from Gram-negative bacteria like Klebsiella and Escherichia, which are implicated in conditions such as human atrial fibrillation (AF)." (PMID 38790263, 2024). "This study was aimed at exploring whether silencing of TLR4 could inhibit atrial fibrosis and susceptibility to atrial fibrillation (AF) by regulating NLRP3-TGF-β in hypertensive rats." (PMID 35860690, 2022). "MiR-4798-3p was indicated to modulate TLR4 and STAT3, and it was closely linked with the prevalence of atrial fibrillation in males and also could regulate genes involved in the pathogenesis of AF." (PMID 37422588, 2023). "SGLT-2i dapagliflozin may prevent diabetic rats' atrial remodeling and reduce the inducibility of atrial fibrillation partly by targeting TLR4/IRAK1/TRAF6/NF-κB inflammatory pathway." (PMID 36148071, 2022). "To assess the involvement of Toll-like Receptor 4 (TLR4) in atrial fibrillation (AF), we conducted a comprehensive analysis using data retrieved from the Gene Expression Omnibus (GEO) database." (PMID 38790263, 2024). "In the present study, we have explored the involvement of Toll-like Receptor 4 (TLR4) in atrial fibrillation (AF), by using a meta-analysis of publicly available human transcriptomic data." (PMID 38790263, 2024). "TLR4/IRAK1/TRAF6/NF-κB, collagen I proteins expressions and incidence of atrial fibrillation (27.3%) were increased in DM group." (PMID 36148071, 2022). "Furthermore, CTRP9 inhibits, at least partly via AMPK, Toll-like receptor 4 (TLR4) signaling and the Smad2,3-pathway in macrophages in the context of atrial fibrillation after MI." (PMID 36831095, 2023). "Finally, in order to reveal the possible mechanism, we verified the role of TLR4/IRAK1/TRAF6/NF-κB in the inhibition of atrial remodeling and atrial fibrillation by DAPA." (PMID 36148071, 2022). "The present study showed CRP-induced activation and cross-talk of TLR4/NF-κB/TGF-β1 signaling pathway in a cardiomyocyte model, which may provide a potential target for future therapeutic interventions in inflammation-induced atrial fibrillation." (PMID 31391207, 2019).
breast tumor (15 papers, 2010 to 2023). "To corroborate the clinical association of S100A7 with TLR4 expression, we analyzed tissue microarrays (TMAs) that contain malignant breast tumors and their adjacent normal control samples." (PMID 33969603, 2022). "The whole‐body deletion of TLR4 was also found to increase breast tumor growth and distant lung metastasis." (PMID 33969603, 2022). "TLR4 expression was found to be significantly low in breast tumor tissues as compared to their normal adjacent breast samples." (PMID 33969603, 2022). "In vivo, we showed that LPS stimulation increased TLR4 expression in MDA-MB-231 breast tumors in nude mice as determined by immunohistochemistry." (PMID 25299052, 2014). "While in particular, silencing of TLR4 promotes tumor progression and lung metastasis which exerts a negative role at the cancer cell level in a murine metastatic breast tumor model." (PMID 25299052, 2014). "Overall, these findings suggest that the commensal microbiota of breast tissue may enhance breast tumor burden through a novel LPS/S100A7/TLR4/RAGE signaling axis." (PMID 33969603, 2022). "Notably, numerous studies have demonstrated the essential role of Toll‐like receptor 4 (TLR4) in anticancer immunity and breast tumor elimination by activating different immune cells, especially CD8+ T lymphocytes." (PMID 33969603, 2022). "Although taxanes can induce the production of inflammatory cytokines through activation of TLR4 in both murine macrophages, and certain tumor cell types, we have observed that this response can occur independently of TLR4 in the MDA-MB-231 breast tumor cell line." (PMID 28915246, 2017). "Proliferation of TLR4-expressing breast tumors has also been stunted with TLR4-inhibition in vitro." (PMID 24887394, 2014). "Vaccination with Ad-BD2-E1A (E1B-deleted oncolytic adenovirus expressing beta-defensin-2) vaccine inhibited primary breast tumor growth and blocked metastasis in a TLR4 dependent manner, thus suggesting the critical role of TLR4 in the induction of anti-tumor immunity by Ad-BD2-E1A." (PMID 24904578, 2014). "This occurrence in vitro may indicate us that TLR4 knockdown in vivo could inhibit the growth and promote the death of breast tumors." (PMID 20618976, 2010). "Moreover, TLR4 ligands promote breast tumor progression via TLR4/NF-κB/STAT3 signaling." (PMID 29928275, 2018). "discuss the functional role of breast tumor microbiota‐derived lipopolysaccharide, which enhances cancer growth through differentially regulating the S100A7/TLR4 expression." (PMID 33969603, 2022). "TLR4 and TLR9 are highly expressed in M13MDA-435-1 and -3 hybrid breast tumor cells, while their cultivation in the presence of the TLR4 ligand lipopolysaccharide induces apoptosis in all hybrid clones." (PMID 35242760, 2022). "breast tumor myeloid cells, the expression of 5 TLR genes (TLR1, TLR2, TLR4, TLR7 and TLR8) were detected in >10% of cells and at moderate to high expression levels." (PMID 34956864, 2021). "TLR3, TLR4, and TLR9 have been shown to be highly expressed in human breast tumors." (PMID 24904578, 2014).